MDM2 (MDM2 proto-oncogene)
Diseases named in the same sentence as MDM2 in open-access papers (continued):
Sharing a sentence is not in itself a finding about the gene and the disease.
tumor (continued). "In addition, detection of MDM2 gene amplification was performed by fluorescence in situ hybridization analysis, and the tumor was positive for amplification of the MDM2 gene." (PMID 33422117, 2021). "Moreover, we further investigated the effect of MDM2 on TRIM31-mediated tumor growth, TRIM31-deficient MCF7 cells were introduced sgRNA targeting MDM2." (PMID 34650049, 2021). "The IHC findings disclosed that smooth muscle actin (SMA) and mouse double minute 2 (MDM2) markers were positive in the majority of the tumor cells; additionally, high-molecular-weight caldesmon (h-caldesmon) and Friend leukemia insertion-1 (Fli-1) markers were positive in some tumor cells." (PMID 34715885, 2021). "Another study suggested that HDAC inhibition reduced MDM2 expression and tumor growth in DDLPS." (PMID 34834427, 2021). "Consequently, increased expression of MDM2 was found in the tumor tissues compared to that in normal tissues." (PMID 34592889, 2021). "Overexpression of Mdm2 plays a critical factor in the tumor cells’ resistance to radiotherapy." (PMID 34502494, 2021). "Thus, to examine the uptake and specificity of [18F]1 by MDM2 expressing tumor cell lines, MCF-7 and HepG2 cells were treated with 0, 1, 5, or 10 μM SP-141 for 21 h, and then assessed for [18F]1 uptake for 1 h." (PMID 33924734, 2021). "We could see from the left-most panel, which displays the gene expression levels (log2 TPM) against tumor purity, that MDM2 expression was higher in the microenvironment in EC (cor = –0.116, P = 0.048)." (PMID 34170849, 2021). "The precise characterisation of tumour genetic background and cancer type should improve the response to MDM2 inhibition and could help to design appropriate combination therapies." (PMID 34911439, 2021). "Additionally, it was observed that the combined treatment CisPt + RSV amplified the MDM-2 gene expression in PE/CA-PJ49 tumor cells more than the effect induced by CisPt alone (p < 0.003, **) or RSV alone (p < 0.004, **)." (PMID 34204834, 2021). "When cancer cells are treated with chemotherapy, MDM2 can be easily released from the interaction and degraded, resulting in effective homologous recombination DNA repair, which translates into the acquisition of a chemoresistant phenotype by the tumor." (PMID 34572735, 2021). "In addition, we also analyzed the effect of MDM2 overexpression on Trim31-mediated tumor growth suppression." (PMID 34650049, 2021).
tumor (continued). "Moreover, RG7112 inhibited tumor growth in a dose-dependent manner in human OS xenografts with MDM2 gene amplification and MDM2 protein overexpression." (PMID 34503094, 2021). "This tumor was MDM2 positive and was located in the anterior arm." (PMID 34671190, 2021). "In conclusion, the LNC CRYBG3/eEF1A1/MDM2/MTBP axis is a novel signaling pathway regulating tumor metastasis and may be a potential therapeutic target for NSCLC treatment." (PMID 33809929, 2021). "Recently increasing studies showed that MDM2 performs important functions in tumor progression." (PMID 32328195, 2020). "Furthermore, NEAT1 modulated the expression of MDM2 via functioning as a ceRNA to sponge miR-590-3p and miR-590-3p was validated as a tumor suppressor in ESCC progression and angiogenesis." (PMID 33680941, 2020). "Cell lines with high MDM2 expression were more resistant to T cell-mediated tumor killing." (PMID 32655895, 2020). "MDM2 amplification has been reported in multiple tumor types." (PMID 32997401, 2020).
tumor (continued). "Targeting MDM2 might therefore be a promising way to extend the spectrum of therapeutic options for this aggressive neoplasm." (PMID 32352245, 2020). "Our findings show that targeting MDM2 attenuates IL-6 expression in tumor cells which may play a crucial role in sensitizing tumor cells to T-cell-mediated killing." (PMID 32655895, 2020). "The discovery of cellular targets that are regulated by MDM2 activity might lead to improved combinatorial strategies that potentiate the anti-tumor effects of Nutlin-3." (PMID 32874188, 2020). "Importantly, NEAT1 functioned as a competing endogenous RNA for miR-590-3p to regulate MDM2 expression and miR-590-3p acted as a tumor suppressor in ESCC progression and angiogenesis." (PMID 33680941, 2020). "Also, SMURF2 and Mdm2 that acts as a potent tumor suppressor in normal cells, can behave as an oncogene in established tumors." (PMID 33260674, 2020). "According to GSEA based on MDM2 expression, the ERBB2 and tumor angiogenesis pathways activated by MDM2 amplification may serve as important pathways inducing primary resistance to EGFR-TKIs." (PMID 32611363, 2020). "In WDLPS, the initiating event driving tumor formation is amplification of the MDM2 gene." (PMID 32344731, 2020). "We therefore interrogated whether targeting MDM2 may favor sensitizing tumor cells to T-cell-mediated killing." (PMID 32655895, 2020). "The upregulated expression of the FLT3, MEF2C, NFKBIZ, and MDM2 genes in sarcoid AMs suggests the potential side effect of DEX and it may lead to increased risk of tumor cell proliferation." (PMID 32477331, 2020).
tumor (continued). "The core functional domain of MDM2 could recognize the N‐terminal transactivation domain and subsequently inhibit the tumor suppressor at the transcriptional level." (PMID 32997401, 2020). "Recently, a study reported on five patients experiencing hyper-progression who had NGS performed on pretreatment tumor tissue, and it confirmed CNAs in MDM2/MDM4, epidermal growth factor receptor (EGFR), and several genes located on 11q13 associated with hyper-progression." (PMID 32903763, 2020). "MDM2 rs2279744 (MDM2 309T>G) and rs3730485 (MDM2 del1518) and MDM4 rs4245739 (MDM4 34091 C>A) variants were reported to influence the genes activity being associated with carcinogenesis and tumor progression." (PMID 32492903, 2020). "To further investigate whether MDM2 blockade may lead to sensitization of tumor cells to T-cell-mediated killing, we pre-treated tumor cells with 0 or 1 μM AMG-232 for 8 hours followed by T-cell co-culture with 0 or 1 μM AMG-232 for another 16 hours." (PMID 32655895, 2020). "Therefore, MDM2 amplification activates multiple pathways and enables tumor cells to develop resistance to EGFR-TKIs." (PMID 32611363, 2020). "In addition, MDM2-mediated FOXO3a degradation can inhibit FOXO3a-mediated apoptosis during tumor development." (PMID 32636834, 2020). "MDM2 amplification may activate the bypass signaling pathways, inhibit tumor cell apoptosis, promote the epithelial to mesenchymal transition (EMT) process and tumor angiogenesis and contribute to primary resistance to EGFR-TKIs." (PMID 32611363, 2020). "However, on digital slides, a semiquantitative assessment of the tumor burden in the mice indicated that MDM2 knockdown and MDMX knockdown reduced metastasis." (PMID 30642351, 2019).
tumor (continued). "Another gene that is important in cell cycle regulation, tumor growth, and angiogenesis is MDM2." (PMID 30700046, 2019). "The tumor-promoting effect of MDM2 in GBMs has been reported in prior publications." (PMID 31534534, 2019). "Importantly, we detected slower tumor growth in the MDM2 knockdown group than in the vector control group." (PMID 30642351, 2019). "As a result, MDM2 overexpression may be a key factor in the insensitivity of tumor cells to radiotherapy." (PMID 31440117, 2019). "Nonsense mutations are often not directly associated with RNA decay, however RNA-seq analysis showed significant upregulation of downstream transcripts in the SMO-SUFU-GLI pathway, including those encoding MDM2 and IGFBP6, which are associated with tumor proliferation." (PMID 31023376, 2019). "Originally, the interest in studying MDM2 in the endothelial cells was initiated by the observation that MDM2 could enhance the production of pro-angiogenic factors in tumor cells." (PMID 31921839, 2019). "Given that HBP1 is a tumor suppressor, MDM2 might affect tumorigenesis and response to oncogenic growth factor signaling by downregulation of HBP1." (PMID 30816344, 2019). "We investigated whether the reduced CTCs correlated with knockdown of MDM2 or MDMX might be a result of reduced primary tumor size at any point during the tumor development." (PMID 30642351, 2019). "We identified both known and novel somatic copy number aberrations (12p, MDM2, and RHBDD1) and mutations (XRCC2, PIK3CA, RITA1) including candidate markers for platinum resistance that were present in a primary tumor of mixed histology and that remained after tandem autologous stem cell transplant." (PMID 30870501, 2019). "In OSA, PML has significantly different expression levels among OSA cell lines, and, as a suppressor gene in an OSA cell line, PML has been demonstrated to physically and functionally interact with oncogene MDM2 to regulate the biological behavior of tumor cells." (PMID 32039036, 2019).